EZH2 (enhancer of zeste 2 polycomb repressive complex 2 subunit)
Diseases named in the same sentence as EZH2 in open-access papers (continued):
Sharing a sentence is not in itself a finding about the gene and the disease.
lung cancer (continued). "MiRNA-377, miRNA-382 and miRNA-498 are considered as tumor-suppressor factors in non-small cell lung cancer and their overexpression suppresses lung cancer growth via EZH2 down-regulation." (PMID 35236381, 2022). "We also found that ectopic EZH2 expression attenuates FAK-inhibition-induced cellular senescence in lung cancer cells." (PMID 36009484, 2022). "EZH2 is known to play an important role in the occurrence, development and metastasis of cancer, while studies have demonstrated that many lncRNA promote the function of lung cancer cells by interacting with EZH2 to silence tumor suppressor factors." (PMID 36339610, 2022). "Silencing miRNA-21/EZH2 axis enhances the potential of radiotherapy and chemotherapy suppressing lung cancer by 39.2% and 69.7%." (PMID 35236381, 2022). "When HADC2 and EZH2 were inhibited by siRNAs in human lung cancer cell line A549, miR-148a expression levels also significantly increased." (PMID 35892859, 2022). "Inhibition of EZH2 expression in lung cancer was recently described as sensitizer to anticancer treatment." (PMID 35351890, 2022). "The upstream signaling events that lead to EZH2 activation and subsequent cisplatin resistance in lung cancer (mainly NSCLC) possibly include the SETD1A/Wnt/β-catenin feedback loop, VEGF/VEGFR2 signaling, and AFAP1-AS1." (PMID 36230683, 2022). "The miRNA-26a has negative correlation with EZH2 in cytotoxic T cells and inhibits EZH2 signaling to disrupt T cell function and to enhance lung cancer progression." (PMID 35236381, 2022). "In fact, EZH2 has been shown to be overexpressed in many cancers, including hepatocellular carcinoma, breast, bladder, and lung cancer." (PMID 35955891, 2022). "It has been widely reported that EZH2 can be recruited by lncRNAs to regulate the development of lung cancer." (PMID 35291911, 2022). "Enhancer of zeste homolog 2 (EZH2) is the enzymatic subunit of polycomb-repressive complex 2 and contributes to transcriptional silencing in the development of lung cancer." (PMID 34838012, 2021). "The effects of targeting EZH2 and G9a on lung cancer prevention was assessed in the A/J mouse lung tumor model." (PMID 33632299, 2021). "It has been described that acetylated EZH2 exerts a gain-of-function in cells and promotes lung cancer progression." (PMID 34277422, 2021). "For example, miR-92b-3p had low expression in lung cancer cells and inhibited the proliferation and invasion of lung cancer cells by targeting EZH2." (PMID 34283053, 2021). "Following this information, EZH2 inhibitors were tested in vivo on KRAS-driven Utx knockout lung cancers and results showed Utx knockout models to be sensitive to EZH2 inhibitors." (PMID 34781949, 2021). "EZH2 altered stem-like phenotypes and progression of lung cancer via regulating the malignant gene modifier (histone methyltransferase)." (PMID 34745015, 2021). "Overexpression of HOTAIR promotes cell cycle progression by silencing p16 and p21 cooperating with EZH2 in human drug-resistant lung cancer cells." (PMID 34405017, 2021). "Gambogenic acid (an EZH2 inhibitor) is a natural compound derived from gamboge and is reported to be used as an antitumor drug in nasopharyngeal and lung cancer." (PMID 35059393, 2021). "EZH2 is overexpressed in prostate, breast, kidney, and lung cancers in which EZH2 up-regulation induces cell migration, colony formation, and genomic instability." (PMID 32784607, 2020). "Profiling the epithelial‐mesenchymal transition‐related molecular markers demonstrated decreased CDH1, TJP1, and OCLN and increased ZEB1, FN1, and EZH2 in response to CDKN2A silencing in lung cancer cells." (PMID 33155773, 2020). "Taken together, these results indicated that knockdown of EZH2 inhibited migration and invasion of lung cancer cells." (PMID 31855281, 2020).
lung cancer (continued). "Culturing lung cancer cells as pulmospheres to promote their differentiation caused decreased levels of LAT1, CD98 and EZH2 proteins." (PMID 33086625, 2020). "They discovered that PCAF-mediated EZH2-K348 increases EZH2 stability, facilitates its capacity in repression of its target genes, and strengthens lung cancer cell migration and invasion." (PMID 33308321, 2020). "Lung cancer tissues demonstrate increased levels of EZH2 acetylation at K348 compared to those observed in normal lung tissues." (PMID 32448308, 2020). "Human lung cancer cell lines A549 and A129L were first transfected with shRNAs for knocking down of EZH2, as shown by qRT‐PCR and Western blot analysis." (PMID 31855281, 2020). "The original analysis of RNA expression indicated considerably higher EZH2 expression level in lung cancer tissues than in the paracancerous lung tissues (P < 0.01)." (PMID 33276757, 2020). "The results showed that the number of chemotactic‐migrated macrophages was increased when EZH2 was overexpressed in lung cancer cells, indicating that EZH2 enhanced the chemotaxis of macrophages." (PMID 31855281, 2020). "This indicates that EZH2 overexpression leads to poor prognosis in patients with lung cancer and is positively correlated with the expression of the immunosuppressive molecule PD-L1." (PMID 33299862, 2020). "EZH2 was also highly expressed in lung cancers with positive KRAS expression, and the correlation was positive in lung adenocarcinoma (r = 0.3129 and p < 0.001)." (PMID 33299862, 2020). "Then, we explored the role of CCL5 in EZH2‐mediated migration and invasion of lung cancer cells and performed cell wound‐healing and transwell assays." (PMID 31855281, 2020). "The in vivo subcutaneous xenotransplanted tumor model also revealed that silence of EZH2 suppressed lung cancer metastasis and macrophages infiltration via regulation of CCL5." (PMID 31855281, 2020). "In lung cancer, EZH2 was upregulated and increased H3K27me3 to repress Dickkopf‐1 (Dkk‐1) expression." (PMID 31855281, 2020). "The results of the TCGA database showed that the expression of EZH2 in normal tissues was lower than that in lung cancer tissues (p < 0.05)." (PMID 33299862, 2020). "In these studies, EZH2 expression was detected in lung cancer tissues in 2180 cases, including 1064 cases in which EZH2 was highly expressed." (PMID 33299862, 2020). "The results showed that the expression of EZH2 in lung cancer tissues was significantly different from that in normal tissues (p < 0.05), and there was a significant correlation between EZH2 expression and the cancer stage (p < 0.05)." (PMID 33299862, 2020). "Enhancer of zeste homolog 2 (EZH2), which is a member of the Polycomb group of proteins that catalyze trimethylation of histone H3 lysine 27 (H3K27me3), was downregulated in lung cancer and associated with NFE2L2 gene silencing." (PMID 32938017, 2020). "In an experiment, it was found that a lentivirus expressing shRNA mediated EZH2 gene knockdown, inhibiting the mRNA and protein expression levels of PD-L1, thereby delaying the progression of lung cancer in vivo by enhancing the antitumor immune response." (PMID 33299862, 2020). "Mechanistically, the promotion ability of EZH2 on cell migration and invasion of lung cancer was also inhibited by CCL5 knockdown." (PMID 31855281, 2020). "The present study indicated that EZH2 knockdown decreasedthe expression of MMP2/9, suggesting that EZH2 knockdown exerted tumor suppressor role in lung cancer cells." (PMID 31855281, 2020). "Although the oncogenic function of PCAF had originally been identified to be induced by adenoviral E1A infection 5, it was also found to promote lung cancer progression by priming EZH2 acetylation." (PMID 31908141, 2020). "By contrast, when EZH2 was upregulated in lung cancer cells, the number of migrated macrophages was increased." (PMID 31855281, 2020).
lung cancer (continued). "EZH2 K348 acetylation is important for silencing its target genes and enhancing the migration and invasion abilities of lung cancer cells in vitro." (PMID 32448308, 2020). "To further validate the clinical significance of EZH2 on TME of lung cancer cells, we determined the lung metastasis through HE staining." (PMID 31855281, 2020). "Our results showed that EZH2 can regulate lung cancer invasion and migration via inhibiting recruitment of macrophages." (PMID 31855281, 2020). "Transwell assay in the present study showed that the number of migrated macrophages was decreased when EZH2 was downregulated in lung cancer cells." (PMID 31855281, 2020). "Taken together, EZH2 knockdown in lung cancer cells inhibited chemotaxis of macrophages and decreased CCL5 expression." (PMID 31855281, 2020). "Wound‐healing and transwell assays results showed that migration and invasion of lung cancer cells was inhibited by EZH2 deletion." (PMID 31855281, 2020). "The results showed that the number of chemotactic migrated macrophages was significantly decreased when EZH2 was silenced in lung cancer cells, indicating that EZH2 knockdown inhibited the chemotaxis of macrophages." (PMID 31855281, 2020). "More importantly, combinative treatment significantly inhibited the EMT and hence impeded the in vivo tumour development via down‐regulation of an oncogenic histone methyltransferase and gene transcriptional regulator EZH2 in lung cancer cells." (PMID 32248643, 2020). "The purpose of this study is to investigate the effect of combination of EZH2 inhibitor and gefitinib on the proliferation, apoptosis and migration of Gefitinib-resistant lung cancer cells." (PMID 31109434, 2019). "LncRNA TUG1 was expressed at low levels in lung cancer cells, which is involved in lung cancer cell growth by regulating LIMK2b via EZH2." (PMID 30925672, 2019). "Our findings provide future perspectives for new pharmacological approach in the treatment of COPD patients, suggesting EZH2 as innovative therapeutic target to prevent biomolecular transition of COPD toward lung cancer." (PMID 31666665, 2019). "Next, there are several epigenetic regulators other than EZH2, which are reported to be associated with poor survival and to be regulator of EMT in lung cancer." (PMID 31042721, 2019). "In conclusion, the cellular and molecular mechanisms associated to EZH2 and DAB2IP regulation represent a potential link between chronic inflammation and COPD progression towards lung cancer." (PMID 31666665, 2019). "Epithelial-mesenchymal transition (EMT) and the histone methyltransferase Enhancer of Zeste Homologue 2 (EZH2) are important regulators of lung cancer progression and metastasis." (PMID 31042721, 2019). "For example, overexpression of EZH2 is highly correlated with a poor prognosis of prostate, breast, kidney and lung cancer." (PMID 33912356, 2019). "With the development of epigenetics, the researchers found that enhancer of Zeste homolog 2 (EZH2) is highly expressed in lung cancer tissue and its expression is closely related to the prognosis." (PMID 31109434, 2019). "The research indicated that proliferation and apoptosis in lung cancer cells were inhibited via a miR-26b-5p-EZH2-mediated approach." (PMID 30124166, 2018). "Ever since then, more selective EZH2 inhibitors with better anti-lung cancer effects have been identified." (PMID 30002791, 2018). "Overall, these data suggest that the in vivo inhibition of Ezh2 in animals with lung cancer alters the tissue microenvironment." (PMID 30487290, 2018). "The findings of a recent report have established reciprocal inductive interactions between LAT1 and the epigenetic regulator Enhancer of Zeste Homolog 2 (EZH2) in lung cancer cells." (PMID 30103560, 2018). "To further understand its action mode in tumor treatment, we next introduced the EZH2-expressing plasmids into lung cancer cells following treatment." (PMID 30555330, 2018).
lung cancer (continued). "Promoting the differentiation of lung cancer cells by culturing them as pulmospheres caused decreases in the LAT1, CD98, and EZH2 protein levels." (PMID 30103560, 2018). "Animal models were fundamental to better define the role of the methyltransferase EZH2 in lung cancer development." (PMID 30060526, 2018). "Over-expressed EZH2 promotes lung cancer progression in multiple ways involving proliferation, apoptosis inhibition, migration and metastasis." (PMID 30002791, 2018). "Coordinately, silencing EZH2 inhibited lung cancer cell growth by cell cycle disruption and triggering cell death." (PMID 30002791, 2018). "For example, LINC00152/CYTOR (identified within this class) binds and recruits EZH2 to its target promoters p15 and p21 in gastric cancer and IL24 in lung cancer and thereby causes repression of their expression." (PMID 29757368, 2018). "In contrast to the intratracheal procedure, via tail vein injection, efficient lung colonization occurred before genetic depletion, and animals bearing Ezh2-depleted tumors developed lung cancer, possibly because of reduced impact of grafting stress." (PMID 30487290, 2018). "It has been reported that SOX2OT knockdown leads to a G2/M arrest and proliferation inhibition in HCC827 and SKMES-1 lung cancer cell lines with a EZH2 poly comb protein dependent cyclinB1 and cdc2 regulation mechanism." (PMID 30202240, 2018). "Studies using EGFR-mutant lung cancer models showed that EZH2 inhibition increases the sensitivity to topoisomerase II G12D/adenocarcinomas." (PMID 30060526, 2018). "The results of clinical trials and further mechanistic investigations would be essential for the potential application of EZH2 inhibitors in lung cancer treatment." (PMID 30002791, 2018). "For lung cancer, to the best of our knowledge, inhibitors targeting EZH2 and LSD1 demonstrated most prominent anti-tumor effects." (PMID 30002791, 2018). "EZH2 and the production of histone-lysine N-methyltransferase is often highly amplified in various types of human malignancies including lung cancer and breast cancer." (PMID 29459674, 2018). "Our findings support the potential roles of miR-21 and EZH2 in improving the therapeutic efficacy of clinical lung cancer treatments." (PMID 29156731, 2017). "The underlying mechanism and the related pathway involving miR-21 and EZH2, which are important biomarkers and target molecules in the clinical treatment for lung cancer, were explored." (PMID 29156731, 2017). "Our data provide positive evidence that EZH2 and miR-21 are highly expressed in LCSCs, which are suggestive of their important roles in the biological behavior of lung cancer." (PMID 29156731, 2017). "Novel anti-lung cancer agents that target proteins such as EGFR or Enhancer of zeste homolog 2 (EZH2) combined with chemotherapy or radiotherapy have been reported." (PMID 29156731, 2017). "In conclusion, our study provides direct evidence that miR-21 and EZH2 knockdown can reduce the biological behavior of human lung cancer stem cells in vitro." (PMID 29156731, 2017). "EZH2 suppresses Dkk1 transcription via trimethylation of H3K27me3, which has been detected in lung cancer." (PMID 28332284, 2017). "In network, 4 pseudogenes (RRP7B, RPLP0P2, MSTO2P and AFG3L1P) co-methylated with EZH2, suggesting an involvement in the progression of lung cancer." (PMID 28938616, 2017). "EZH2 inhibitors would be good candidates because of EZH2 oncogenic status in lung cancer, and some are in clinical development." (PMID 28672805, 2017). "In this study, we investigated the effects of miR-21 and EZH2 on the biological behavior of human lung cancer stem cells in vitro." (PMID 29156731, 2017). "In this review, epigenetics regulation of EMT was described in lung cancer with a particular interest in EZH2, an oncogene in lung tumors." (PMID 28672805, 2017).
lung cancer (continued). "Taken together, our results indicate that both miR-21 and EZH2 are essential for the proliferative potential and colony-formation capacity of lung cancer cells." (PMID 29156731, 2017). "Our present meta-analysis is the first to evaluate the correlation between EZH2 overexpression and survival in patients with lung cancer." (PMID 26754405, 2016). "If this is indeed the case, forced overexpression of EZH2 is likely to increase the resistance of lung cancer cells to curcumin." (PMID 27049834, 2016). "Based on RNA sequencing from the database, HBP1 and p21 were frequently down-regulated in uterine cancer, colon cancer, rectum cancer, lung cancer, liver cancer, and stomach cancer, whereas EZH2 was frequently up-regulated in these cancers." (PMID 27129219, 2016). "Curcumin inhibits lung cancer cell proliferation and EZH2 expression, and several studies suggest that ezh2 is a candidate oncogene." (PMID 27049834, 2016). "Subsequently, elevated expression of EZH2 has already been demonstrated to promote cancer cell proliferation in multiple cancers, including bladder cancer, lung cancer, hepatocellular carcinoma and gastric cancer." (PMID 27092879, 2016). "In the present study, we provided evidences that curcumin suppressed the expression of enhancer of zeste homolog 2 (EZH2) in lung cancer cells both transcriptionally and post-transcriptionally." (PMID 27049834, 2016). "EZH2 inhibition enhances the sensitivity to MEK-ERK or PI3K/AKT targeted therapies in specific KRAS-mutant lung cancer cells and tumors." (PMID 27494834, 2016). "This meta‐analysis combined 10 publications including 1461 patients with lung cancer to yield statistics, indicating different roles of EZH2 on OS in oesophageal cancer, gastric cancer and colorectal cancer." (PMID 26859127, 2016). "Our investigation is the first to extensively explore the relationship between curcumin and EZH2 in lung cancer cells and the reciprocal regulation between EZH2 and NOTCH1." (PMID 27049834, 2016). "All of the studies reported the prognostic value of EZH2 status for survival in patients with lung cancer." (PMID 26754405, 2016). "Our study is the first to investigate curcumin's regulation of EZH2 and the mechanism by which curcumin inhibits the expression of EZH2 in lung cancer cells." (PMID 27049834, 2016). "We performed a meta-analysis of 10 studies (n = 1,695 patients) that evaluated the correlation between EZH2 overexpression and survival in patients with lung cancer." (PMID 26754405, 2016). "Mechanistically, our results indicated that the activation of phosphorylation of SAPK/JNK signaling, regulation and interaction between p65, DNMT1, and EZH2 protein/gene were involved in the anti-lung cancer effect of PPI in this process." (PMID 27421653, 2016). "qPCR and western blot analysis showed that curcumin significantly downregulated EZH2 mRNA and protein expression in lung cancer cells." (PMID 27049834, 2016). "The meta analysis combined 10 publications including 1,695 patients with lung cancer to yield statistics, indicating statistically significant role of EZH2 on overall survival in lung cancer." (PMID 26754405, 2016). "It is also reported that miR-101 inhibits lung cancer invasion through regulation of EZH2, which inhibits cell proliferation and invasion, but enhances paclitaxel-induced apoptosis in non-small cell lung cancer." (PMID 26633386, 2015). "The combination of TSA and EZH2 knockdown led to robust induction of miR-139, which confirms that H3K27me3 is involved in the silencing of miR-139 in lung cancer." (PMID 26256448, 2015). "EZH2 deregulation is frequently detected in a variety of cancer types, including lung cancer, prostate cancer and UBC, by regulating its multiple target genes involved in carcinogenesis." (PMID 26484567, 2015). "EZH2 is one of the targets currently being evaluated for the treatment of lung cancer; it is the catalytically active component of the PRC2 complex." (PMID 24745014, 2014).